BRCA1 (BRCA1 DNA repair associated)
Diseases named in the same sentence as BRCA1 in open-access papers (continued):
Sharing a sentence is not in itself a finding about the gene and the disease.
breast cancer (continued). "Significantly fewer HER2 positive breast cancers including both HR-/HER2+ and HR+/HER2+ were found in patients with GPVs in BRCA1/2 than the non-carriers." (PMID 34336698, 2021). "Our data would suggest that, for women who had a breast cancer where the histology is of a TNT or grade 3 ER-positive HER2-negative phenotype in association with a high MS, there may be merit it considering testing for germline PALB2_PGVs where BRCA1/2 testing was negative." (PMID 34113003, 2021). "In another study, promoter hypermethylation of BRCA1 was observed in 8% (three in 39) of cases with EOC and 1% (six in 613) of cases with breast cancer but in none of 10 age-matched controls." (PMID 33396385, 2020). "Our results show a positive correlation between BRCA1 and CD44, HAS2, HAS3 and HYAL1 in colorectal but not breast cancer." (PMID 32610620, 2020). "The activity of platinum salts was also evaluated in early breast cancer, with proven benefits in the neoadjuvant scenario for the TNBC subtype, regardless of BRCA1 status." (PMID 32481735, 2020). "So, actually, if you want to really help people with this, the genetic test needs to be cheaper, or subsidized, because right now it is not” – 51-year-old female, BRCA1 PV/LPV carrier, with breast cancer." (PMID 33110458, 2020). "Thus, BRCA1 and RAD51C promoter methylation, likely in combination with LOH, may have led to the HRD phenotype for a sizable portion of the ovarian and of breast cancer patients with no clear biallelic loss of the HRD associated genes, and potentially for patients with other cancer types as well." (PMID 33149131, 2020). "Likewise, different actions on persons who are carriers of BrCa1 (frequent screening, prophylactic mastectomy, oophorectomy) will have different actual effects, and will also yield estimates that are different when contrasting carriers and non-carriers for the occurrence of breast cancer." (PMID 31711141, 2020). "In other studies performed in China, higher pathogenic variant frequencies ranging from 0.54 to 1.6% were observed in BRCA1 and BRCA2 negative early-onset and/or familial breast cancer cases." (PMID 33342430, 2020). "These intervals correspond to, neither the previously identified Breast Cancer Cluster Regions (BCCR), nor the Ovarian Cancer Cluster Regions (OCCR) of BRCA1, and only marginally overlap with the BCCRs and the OCCRs of BRCA2." (PMID 30736435, 2019). "Thirty five out of three hundreds (12%) of BRCA1/2-sequencing negative familial breast cancer patients from non-Ashkenazi Jewish in US were found carrying BRCA LCRs, with 10% (31/300) LCRs detected in BRCA1 and 1% (4/300) detected in BRCA2, respectively." (PMID 31174498, 2019). "For women without breast cancer the mean age at BSO was 45.6 years (range 13–78 years), 44.7 years for BRCA1 carriers and 47.7 years for BRCA2 carriers." (PMID 30971774, 2019). "But recently, some studies showed that the expression level of CLDN1 was low in luminal-like and claudin-low breast cancers, while the expression level of CLDN1 was high in basal-like, most ER negative, BRCA1, medullary breast cancers." (PMID 30910845, 2019). "BRCA1/2 are the most analyzed and studied genes in LA countries, few studies report non-BRCA gene status in breast cancer." (PMID 31658756, 2019).
breast cancer (continued). "Very few studies, if any, have been carried out with comprehensive analysis of BRCA1 and BRCA2 in truly unselected breast cancer patients in high-incidence countries without strong founder mutations." (PMID 29164420, 2018). "They found only 1 case of lobular carcinoma in situ [LCIS (0.7%)] and no cases of ductal carcinoma in situ (DCIS) or invasive ductal carcinoma (IDC), even among BRCA1/2MUT carriers." (PMID 30203341, 2018). "We functionally demonstrated the negative correlation between miR-498 and BRCA1 in breast cancer cell lines: inhibition of miR-498 in Hs578T cells increased BRCA1 levels and its overexpression in MCF7 cells reduced BRCA1 expression." (PMID 26933805, 2016). "As one of the three most intensely scrutinized genes in breast cancer (the other two being ESR1 and HER2), there is no molecular mechanism of BRCA1 regulation that has not been examined in primary human breast cancer specimens." (PMID 27077368, 2016). "In conclusion, in contrast to BRCA1/2 breast cancers, no apparent predominant specific CNA profile nor robust gene expression profile for CHEK2*1100delC breast cancers was found." (PMID 26553136, 2015). "According to the findings of the present study BRCA1 and BRCA2 large genomic rearrangements are unlikely to significantly contribute to breast cancer in Sri Lanka." (PMID 24906410, 2014). "Large genomic rearrangements have been characterized in BRCA1 and BRCA2 genes in several populations but these have not been characterized in Sri Lankan breast cancer patients." (PMID 24906410, 2014). "A missense alteration, p.R361Q, resulting in abnormal DNA response, was identified in 3 out of the 125 Finish, BRCA1 and BRCA2 negative, families and one out of the 991 unselected breast cancer cases studied." (PMID 23586058, 2013). "In the present study we used massively parallel sequencing to analyze 7 BRCA1/BRCA2 negative families, each having at least 6 affected women with breast cancer (between 6 and 10) diagnosed under the age of 60 across generations." (PMID 23409019, 2013). "Although the role of SMC1 in the plasma membrane is not known, BRCA1, a SMC1 binding protein has recently shown to be involved in regulation of motility and migration of breast cancer cells." (PMID 23717600, 2013). "All patients had no family history of breast cancer, tested negative for BRCA1 and BRCA2, and had no other known breast cancer risks." (PMID 24151509, 2013). "Furthermore, expansion of the number of BRCA1 mutation carriers by including other family members in addition to the index cases in the study by Hollestelle and colleagues did also not improve significance, nor did the KRAS variant appear to modify breast cancer risk for BRCA1 mutation carriers." (PMID 22436609, 2012). "Since BRCA1-associated breast cancers have pushing borders that prevent them from easily reaching vessels and are often of the medullary (like) type that is known to have a low rate of lympho-vascular invasion (LVI), we hypothesized that absence of LVI could characterize BRCA1 related breast cancer." (PMID 20398395, 2010). "Although no direct links exist between RNF14 and BRCA1, our PPI analysis shows that indirect interactions occur, and they involve important proteins in breast cancer biology, like the estrogen and androgen receptors." (PMID 19695104, 2009).
breast cancer (continued). "The ER-positive breast cancer cells, such as MCF-7 and T47D cells, express BRCA1, whereas the ER-negative tumor cells, such as SKBR3 and MDA-MB231 cells are BRCA1 negative." (PMID 18431487, 2008). "Previous in vitro experiments using breast cancer cells showed that BRCA1-negative cells were less sensitive to paxlitaxel than BRCA1-positive cells, and that BRCA1 might be required for the induction of apoptosis in response to paclitaxel in breast cancer cells." (PMID 19690636, 2007). "ERα formed complexes with wild-type BRCA1 and CBP in E2-treated T47D clones but not in MDA-MB-468 clones, a similar pattern to that observed in the parental breast cancer cell lines." (PMID 16417649, 2006). "It takes into account the simultaneous effects of BRCA1, BRCA2 and the residual familial clustering of breast cancer not accounted by these genes, which is assumed to be explained by a polygenic model." (PMID 16417652, 2006). "Although other noncoding variation in the RAD51 gene may be involved in BRCA1/2-mutation-negative breast cancers, the absence of coding or untranslated region mutations in this set of well-characterised familial cases implies that RAD51 is not a major familial breast cancer predisposition gene." (PMID 16762046, 2006). "BRCA1 2626–2627delAA has not yet been reported in the BIC database and was identified in a sporadic patient diagnosed with breast cancer at the age of 27 years." (PMID 15026808, 2004). "The existing genetic models are either based on a single susceptibility gene or take into account only the effects of BRCA1 and BRCA2 and hence they do not describe the familial breast cancer adequately." (PMID 11857015, 2002). "Despite its reported beneficial effects on psychological and physical symptoms among breast cancer survivors, our results indicate that MBSR may not be beneficial or may even be harmful after RRSO in BRCA1/2 carriers." (PMID 39201170, 2024). "Typically, these criteria were based on early studies of BRCA1 and BRCA2 and are based on age at breast cancer diagnosis, ethnicity (e.g., Jewish), clinical characteristics of breast cancer (e.g., bilateral breast cancer, triple‐negative breast cancer), and family history of cancer." (PMID 36544278, 2023). "Expenditures under the more expensive BRCA1/2 non-panel CPT code 81162 grew consistently until peaking at $118 million in 2019, costing over 10 times more than the amount paid that year for the 81432 breast cancer panel code." (PMID 37435610, 2023). "No PIK3CA, BRCA1, or ERBB2 alterations were identified in the breast carcinoma cases." (PMID 36125633, 2023). "Thus, we next limited our analysis to basal-like breast cancers, and again found a tendency for enhanced EMT/CL-like features in BRCA1 basal-like tumors, however, these differences were not statistically significant when compared to BRCA1 Wt tumors." (PMID 35236825, 2022). "Interestingly, the relationship between iNOS expression and the expression of breast cancer protooncogenes HER2, BRCA1, and BRCA2 in the pathogenesis of breast cancer is not well understood." (PMID 35740092, 2022). "In addition, breast cancer organoid lines characterized by high BRCA1/2 signatures were sensitive to poly (ADP-ribose) polymerase inhibitors; whereas those with low BRCA1/2 signatures were not." (PMID 34520134, 2021). "Survival was not significantly different between BRCA1, BRCA2 and non-BRCA carriers on enhanced screening with 20-year breast cancer specific survival particularly good in 60 BRCA1 carriers at 91.5% (78.5–96.8) compared to 59 BRCA2 at 85.1% (64.1–94.3) and 275 non-BRCA 84.7% (76.5–90.3)." (PMID 34312777, 2021). "However, the risk of developing breast cancer by HRT may differ between BRCA1 and BRCA2 pathogenic variant carriers, and therefore we need to continue discussing carefully whether long-term estrogen treatment does not really increase the risk of breast cancer incidence." (PMID 34071148, 2021).
breast cancer (continued). "Overexpression of a truncated form of BRCA1 lacking its N-terminus ubiquitin ligase domain was found to disrupt endogenous interaction of BRCA1 with ERM and increase spontaneous motility of human breast cancer cells." (PMID 35008272, 2021). "Moreover, one-third of all breast cancer occurs within the families are not related to either BRCA1 or BRCA2, indicating that other low penetrate genes are involved in the development of familial breast cancer." (PMID 33013205, 2020). "For ovarian cancers, although the HRs were of similar magnitude as for breast cancers in BRCA1 and BRCA2 carriers, respectively, the HRs were not significant (BRCA2 carriers, P = 0.10 and BRCA1 carriers, P = 0.11) likely reflecting the smaller number of events." (PMID 32175645, 2020). "Interestingly, the anti-mammary tumor effects of GEN are not observed in Brca1+/− mice, possibly suggesting a requirement for coincident Brca1 expression." (PMID 31652854, 2019). "We did not detect any case with both BRCA1 and MGMT methylations in breast cancer patients." (PMID 30049288, 2018). "Therefore, we compared the expression of BRCA-1 and AhR in human ERα-positive MCF-7, and ERα-negative UACC-3199 sporadic, breast cancer cells." (PMID 26715507, 2015). "Overall, these cell culture studies implied that the effects of αNF, selected as a prototype AhR antagonist, were influenced by cell-context and ERα status, i.e. αNF rescued BRCA-1 and ERα expression in sporadic and ERα-negative UACC-3199 breast cancer cells carrying hypermethylated BRCA-1." (PMID 26715507, 2015). "However, in patients with no methylated BRCA1 in paired tumour DNA, BRCA1 promoter methylation is only specific to WBC and does not directly contribute to breast cancer of those patients." (PMID 25403427, 2014). "The high frequency of epigenetic silencing in BRCA1, BRCA2, and p14 suggests a potential influence of the virus on the methylation machinery, an oncogenic mechanism reported in other cancers but not yet in breast cancer." (PMID 24607238, 2014). "Thus this study demonstrates that BRCA1 and BRCA2 large genomic rearrangements are unlikely to make a significant contribution to aetiology of breast cancer in Sri Lanka." (PMID 24906410, 2014). "The expression of PTEN and BRCA1 in ZR75-1 and HCC1419 breast cancer cells and malignant breast cancer tissues, however, was not negatively correlated with the miR-20b expression, implicating the involvement of other factors/mechanisms in the expression of PTEN and BRCA1, in addition to miR-20b." (PMID 23945289, 2013). "In a Spanish study of 492 BRCA1- and BRCA2 tested-negative breast cancer patients with family history of breast and/or ovarian cancer, they identified 12 variants, of which one was clearly pathogenic in the subset of 106 cases with a family history of both breast and ovarian cancers." (PMID 21980511, 2011). "Indeed, cadmium produced an apparent basal-like breast cancer phenotype, including ER negativity, HER2 negativity, reduced BRCA1 expression, and increased expression of p63 and CK5, all noteworthy characteristics of basal-like human breast cancer phenotype." (PMID 20049202, 2009). "This was compared with the observed numbers of 14 BRCA1, 11 BRCA2 and 25 total carriers (three BRCA2 carriers were among the 42 individuals excluded in the analysis because they had a single case of breast cancer and did not have any family history of cancer in the family)." (PMID 18627636, 2008). "It is not clear whether the prognosis for women with BRCA1 and BRCA2 related breast cancers differs compared to sporadic tumours with similar pathological prognostic indices." (PMID 17697367, 2007).
breast cancer (continued). "Although recent cohort studies suggest a possible survival benefit for prophylactic mastectomy in unaffected BRCA1 carriers, there are no data to suggest a survival benefit relative to MRI surveillance in unaffected BRCA2/PALB2 carriers or carriers with a prior history of breast cancer." (PMID 38248108, 2024). "Moreover, our database analysis (Breast Cancer Gene-Expression Miner v3.2) indicates that there is a statistically significant relationship (p < 0.05, r = −0.27) between reduced expression of BRCA1 and reduced expression of NORE1A in Her2+, but not Her− breast cancers." (PMID 37627161, 2023). "Indeed, our database analysis shows that there is a statistically significant relationship (p < 0.05, r = −0.27) between the reduced expression of BRCA1 and the reduced expression of NORE1A in Her2+, but not Her− breast cancers (Breast Cancer Gene-Expression Miner v3.2)." (PMID 37627161, 2023). "Since constitutional BRCA1 methylation affects a small fraction of normal cells in the individual, one may assume that the background incidence of BRCA1 unmethylated breast cancers (including TNBC) is similar among carriers and non-carriers of BRCA1 constitutional methylation." (PMID 38053165, 2023). "We note that BRCA1 and NF1 were not significant in the primary cancer cohort after correction for multiple hypothesis testing, something we believe to be due to the play of chance given the wealth of data implicating these two genes in primary breast cancer." (PMID 28810143, 2017). "Also, we tested in human estrogen receptor (ER)α-negative sporadic UACC-3199 and ERα-positive MCF-7 breast cancer cells carrying respectively, hyper- and hypomethylated BRCA-1 gene, if the treatment with the AhR antagonist α-naphthoflavone (αNF) modulated BRCA-1 and ERα expression." (PMID 26715507, 2015). "Exogenous expression assays revealed that miR-10b and miR-26a, but not miR-146a, can down-regulate the expression of BRCA1 in both triple-negative MDA-MB-231 and luminal epithelial MCF7 breast cancer-derived cells, whereas miR-153 could down-regulate BRCA1 expression only in MCF7 cells." (PMID 26392359, 2015). "Currently, BRCA1/2 status is the prevailing indicator of potential PARP inhibitor sensitivity, although not all BRCA1/2 breast cancers respond and there is preclinical evidence to suggest that PARP inhibitors may hold benefit in cancer populations beyond BRCA1/2 mutation carriers." (PMID 24625110, 2014). "To verify the hypothesis that the lack of functional BRCA1 is involved in the inappropriate expression of XIST from Xa, we performed BRCA1 silencing in HMEC (XCI-type 0) and in the following BRCA1wt breast cancer cell lines: MDA MB 231(XCI-type 1), T47D (XCI-type 1) and MCF7 (XCI-type 2)." (PMID 19440381, 2009). "Interestingly, the BRCA1 cell line MDA-MB-436, which showed lower levels of the BRCA1 transcript than those found in control breast cancer cell lines measured by quantitative RT–PCR (data not shown), had the same pattern of NFκB-related gene expression as the ESR1-negative-A tumours." (PMID 19826428, 2009). "A total of 289 unrelated reference subjects selected without regard to breast cancer from five population groups (48 each from African-Americans, Chinese-Americans and Mexican-Americans, 60 CEPH subjects, and 85 Ashkenazi Jews) were genotyped across BRCA1, spanning a region of approximately 646 kb." (PMID 17916242, 2007).